DUSP23 (dual specificity phosphatase 23)
Description:
Protein phosphatase that mediates dephosphorylation of proteins phosphorylated on Tyr and Ser/Thr residues. In vitro, it can dephosphorylate p44-ERK1 (MAPK3) but not p54 SAPK-beta (MAPK10) in vitro. Able to enhance activation of JNK and p38 (MAPK14).
Synonyms: LDP-3; LDP3; VHZ; FLJ20442; DUSP25; MOSP
Tractability: Small molecule: a structure with a bound ligand is known. PROTAC: its protein half-life has been measured; a small molecule that binds it is known.
Target class: Phosphatase; Serine/threonine/tyrosine protein phosphatase; Enzyme; Protein Phosphatase
Gene: Protein-coding gene on chromosome 1 (159,780,932 to 159,782,543, forward strand). Ensembl gene ENSG00000158716.
Subcellular location: Cytoplasm, cytosol; Nucleus
Subcellular location (Human Protein Atlas): Nucleoplasm
Gene Ontology:
Molecular function: phosphatase activity; protein binding; protein tyrosine/serine/threonine phosphatase activity; protein tyrosine phosphatase activity; protein serine/threonine phosphatase activity
Biological process: dephosphorylation; cilium assembly
Cellular component: nucleoplasm; cytoplasm; cytosol; nucleus
Genetic constraint (gnomAD): Loss-of-function variants: 10 observed, 12.53 expected, observed/expected ratio (o/e) 0.8, 90% interval 0.49 to 1.35. The synonymous counts are far from expectation, so gnomAD's model fits this gene poorly and the ratio says little. Missense variants: 228 observed, 182.41 expected, observed/expected ratio (o/e) 1.25, 90% interval 1.12 to 1.39. Synonymous variants: 107 observed, 82.86 expected, observed/expected ratio (o/e) 1.29, 90% interval 1.1 to 1.52.
Homologues: Orthologues: chimpanzee DUSP23 (100% identical), macaque DUSP23 (100% identical), guinea pig DUSP23 (97% identical), rabbit DUSP23 (97% identical), rat Dusp23 (97% identical), pig DUSP23 (96% identical), mouse Dusp23 (95% identical), dog DUSP23 (95% identical), zebrafish dusp23b (65% identical), tropical clawed frog dusp23 (65% identical), zebrafish dusp23a (58% identical).
Diseases named in the same sentence as DUSP23 in open-access papers:
DUSP23 is named in the same sentence as 7 diseases in open-access papers, as found by Europe PMC text mining. Sharing a sentence is not in itself a finding about the gene and the disease. The quoted sentences say what the papers report.
autoimmune disease (2 papers, 2021 to 2026). A disorder resulting from loss of function or tissue destruction of an organ or multiple organs, arising from humoral or cellular immune responses of the individual to their own tissue constituents. "Downregulation of DUSP1, DUSP3, DUSP11, and DUSP22, as well as upregulation of DUSP4, DUSP6, and DUSP23 are involved in human autoimmune diseases." (PMID 42087139, 2026). "However, this CpG site is also an eQTM for five other genes in CD4+ T cells (TAGLN2, SLAMF8, DUSP23, PHYIN1 FCRL6), several of which have established autoimmune disease connections." (PMID 34946847, 2021).
Anxiety (1 paper, 2013). Intense feelings of nervousness, tension, or panic often arise in response to interpersonal stresses. "The lower voluntary activity, the higher anxiety (O-maze), and reduced activity (water maze) of B6 allele carriers appear to be mediated by the microdeletion and/or variants in its close proximity that finally modulate expression of genes like Dusp23 and Pcp4l1 presumably in a cis-acting manner." (PMID 23308133, 2013).
neuroblastoma (1 paper, 2011). Neuroblastoma (NB) is the most common solid, extracranial childhood tumor. "We present eight genes (KRT19, PRKCDBP, SCNN1A, POU2F2, TGFBI, COL1A2, DHRS3 and DUSP23) that are methylated in neuroblastoma, most of them not previously reported as such, some of which also distinguish between biological subsets of neuroblastoma tumors." (PMID 21314941, 2011).
systemic lupus erythematosus (1 paper, 2025). An autoimmune multi-organ disease typically associated with vasculopathy and autoantibody production. "DUSP23(Dual-specificity protein phosphatase 23), located on human chromosome 1, is identified as a susceptibility gene for systemic lupus erythematosus." (PMID 40533455, 2025).
DUSP23 also shares sentences with these, for which no sentence is quoted: cancer (2 papers); breast carcinoma (1); invasive ductal carcinomas (1).